PCDH17 (protocadherin 17)
Description:
Potential calcium-dependent cell-adhesion protein.
Synonyms: PCDH68; PCH68
Tractability: Antibody: UniProt places it where antibodies can reach, with medium confidence; UniProt predicts a signal peptide or a membrane-spanning region; its Gene Ontology location is reachable by antibodies, with medium confidence; the Human Protein Atlas places it where antibodies can reach. PROTAC: its protein half-life has been measured.
Gene: Protein-coding gene on chromosome 13 (57,631,744 to 57,729,311, forward strand). Ensembl gene ENSG00000118946.
Subcellular location: Cell membrane
Subcellular location (Human Protein Atlas): Cytosol; Vesicles; Plasma membrane
Gene Ontology:
Molecular function: protein binding; cell adhesion molecule binding; calcium ion binding
Biological process: cell adhesion; presynaptic active zone assembly; homophilic cell-cell adhesion; synaptic membrane adhesion
Cellular component: plasma membrane; GABA-ergic synapse; glutamatergic synapse; membrane; postsynaptic membrane; presynaptic membrane
Genetic constraint (gnomAD): Loss-of-function variants: 21 observed, 71.18 expected, observed/expected ratio (o/e) 0.3, 90% interval 0.21 to 0.43. The upper end of that interval is the gene's LOEUF score, 0.43, which puts it in group 1 of 6, group 1 being the genes least tolerant of losing a copy. Missense variants: 1,471 observed, 1,665.5 expected, observed/expected ratio (o/e) 0.88, 90% interval 0.85 to 0.92. Synonymous variants: 701 observed, 705.04 expected, observed/expected ratio (o/e) 0.99, 90% interval 0.93 to 1.06.
Homologues: Orthologues: chimpanzee PCDH17 (99% identical), macaque PCDH17 (99% identical), dog PCDH17 (99% identical), pig PCDH17 (99% identical), rat Pcdh17 (98% identical), mouse Pcdh17 (98% identical), rabbit PCDH17 (92% identical), tropical clawed frog pcdh17 (83% identical), zebrafish pcdh17 (74% identical). Paralogues in human: PCDH19 (48% identical), PCDH10 (31% identical), PCDH18 (31% identical), PCDHGA12 (27% identical), PCDHAC2 (27% identical), PCDHGB7 (27% identical), PCDH8 (27% identical), PCDHGA4 (27% identical), PCDHGA10 (27% identical), PCDHGA11 (27% identical), PCDHGA7 (27% identical), PCDH12 (26% identical), and 49 more.
Diseases named in the same sentence as PCDH17 in open-access papers:
PCDH17 is named in the same sentence as 59 diseases in open-access papers, as found by Europe PMC text mining. Sharing a sentence is not in itself a finding about the gene and the disease. The quoted sentences say what the papers report.
breast carcinoma (8 papers, 2011 to 2024). "On another note, breast cancer patients with wtCCND1 and unmethylated (unm) PCDH17 achieved higher pCR rate than those with CCND1 amp andmethylated (m) PCDH17 (13.8% (n=1) vs 2.7% (n=1) and 67.3% (n=1) vs 31.6% (n=1), respectively)." (PMID 38576013, 2024). "We suggest that keratin 18 and protocadherin 17 should be further investigated in bitches because of their role in women’s breast cancer." (PMID 39057100, 2024). "It is important to emphasize that the keratin 18 and protocadherin 17 proteins and their coding genes play an important role in the suppression of proliferation and tumor growth in breast cancer in women." (PMID 39057100, 2024). "In recent years, PCDH17 was identified as a tumor suppressor gene for breast cancer, through promoter methylation." (PMID 31772653, 2019). "The biological functions of PCDH17 in breast cancer are unclear." (PMID 27351130, 2016). "Little is known about the molecular mechanisms of PCDH17 during the development of breast cancer." (PMID 27351130, 2016). "Downregulation of PCDH17 in breast cancer was mainly due to the methylation of its promoter." (PMID 27351130, 2016). "Downregulation of PCDH17 and methylation of its promoter were common events in breast cancer." (PMID 27351130, 2016). "We next determined whether promoter methylation is involved in PCDH17 downregulation in breast cancer." (PMID 27351130, 2016). "PCDH17 silencing via promoter methylation in breast cancer suggests that it might function as a TSG." (PMID 27351130, 2016). "This implies that PCDH17 could possibly act as a suppressor of breast cancer stemness and plays a role in the initiation of the disease, which is worth looking into." (PMID 27351130, 2016). "Here, we examined the abnormalities and functions of PCDH17 in breast cancer pathogenesis." (PMID 27351130, 2016). "Indeed, PCDH17 was shown to be an inhibitor of the Wnt/β-catenin signaling in breast cancer; the same might also hold true in AML." (PMID 30922328, 2019). "Therefore, it is possible that PCDH17 could be an antagonist of Wnt/β-catenin signaling in breast cancer." (PMID 27351130, 2016). "Thus, PCDH17 promoter methylation could be a potential biomarker for the diagnosis of breast cancer." (PMID 27351130, 2016). "Thus, we found that PCDH17 functions as a tumor suppressor inhibiting Wnt/β-catenin signaling and metastasis in breast cancer but is frequently methylated in primary tumors which could be a potential biomarker." (PMID 27351130, 2016). "It is unclear whether PCDH17 acts as a TSG in breast cancer." (PMID 27351130, 2016). "The groups with mammary neoplasms (GI and GII) showed a higher abundance of the proteins protocadherin 17 and albumin." (PMID 39057100, 2024). "Protocadherin 17 (PCDH17) functions as a tumour suppressor downregulating Wnt/β-catenin signalling and cell metastasis and is frequently methylated in breast cancer." (PMID 31703382, 2019). "We failed to observe any correlation between PCDH17 expression levels and clinicopathological characteristics of breast cancer." (PMID 27351130, 2016). "To this end, we checked the expression of NRCAM and PCDH17 in breast cancer cell lines expressing ESR1 (MCF-7 cells) or not expressing ESR1 (MDA-MB-231 cells) and examined whether the expression of these putative ER-regulated genes is ER-dependent." (PMID 21281495, 2011).
colorectal cancer (7 papers, 2014 to 2025). A primary or metastatic malignant neoplasm that affects the colon or rectum. "A treatment of colorectal cancer cells (HT-29) with Se-allylselenocysteine (ASC) has been shown to induce a demethylation of the PCDH17 promoter associated with an increase in PCDH17 expression and an activation of autophagy." (PMID 31861179, 2019). "All these data showed that PCDH17 expression was correlated with sensitivity to 5-FU and autophagy in colorectal cancer patients." (PMID 31815010, 2019). "Frequent epigenetic inactivation of PCDH17 was also reported in gastric and colorectal cancers, in which PCDH17 exerts its tumor suppressive activity by inducing apoptosis and autophagy." (PMID 30922328, 2019). "We previously identified PCDH17, encoding protocadherin 17, as a frequently methylated and downregulated tumor suppressor gene (TSG) in gastric and colorectal cancers." (PMID 27351130, 2016). "PCDH17 (Protocadherin 17), a tumor suppressor frequently methylated in gastric and colorectal cancers, was highly methylated in AGS cells." (PMID 25322458, 2014). "Firstly, the number of CD31-positive cells and the number of PCDH17 and CD31 co-positive cells in colorectal cancer tissues were counted respectively." (PMID 39837826, 2025). "The tumor suppressor gene (TSG) PCDH17 (Protocadherin 17), which is an activator of autophagy, has been shown to be frequently silenced by promoter hypermethylation in gastric and colorectal cancers, but not in normal tissues." (PMID 31861179, 2019).
bladder cancer (5 papers, 2016 to 2025). "In our study, we confirm that PCDH17 is also a strong predictor of bladder cancer outcome in patients undergoing surgery." (PMID 31772653, 2019). "PCDH17 promoter methylation is closely related with malignant behavior and may be regarded as an independent predictor of clinical outcomes in bladder cancer." (PMID 31772653, 2019). "PCDH17 promoter methylation was significantly correlated with advanced stage and high grade tumors, revealing that PCDH17 might therefore be a prognostic target in bladder cancer." (PMID 31772653, 2019). "Here, we established a combination methylation assay of HOXA9, ONECUT2, PCDH17, PENK, TWIST1, VIM and ZNF154, which had displayed great prediction accuracy of bladder cancer in patients with hematuria by using urine samples." (PMID 31777606, 2019).
bladder cancer (continued). "In conclusions, a urinary combined methylation assay of HOXA9, ONECUT2, PCDH17, PENK, TWIST1, VIM and ZNF154 displayed accurate prediction of bladder cancer in hematuria patients, which provided the guidance for the patients at early stage tumor and during the follow-up after operation." (PMID 31777606, 2019).
cardiac hypertrophy (5 papers, 2020 to 2026). "Research indicates that SP1-induced SNHG14 aggravates cardiac hypertrophy by sponging miR-322-5p and miR-384-5p to upregulate protocadherin 17 (PCDH17), making SNHG14 a potential biomarker for cardiac hypertrophy." (PMID 41602333, 2026). "The report also suggested that lncRNA SNHG14 (small nucleolar RNA host gene 14) was validated to sponge both miR-322-5p and miR-384-5p to elevate PCDH17 levels in vivo and in vitro cardiac hypertrophy models." (PMID 37342178, 2022). "Furthermore, knockdown of SP1 was reported to restrain Ang-II-induced cardiac hypertrophy by regulating the ceRNA network of SNHG14/miR-322-5p/miR-384-5p/PCDH17." (PMID 35048778, 2022).
colon cancer (5 papers, 2013 to 2025). "Among these mutations, PCDH17 has been identified as a driver gene that induces colon cancer tumorigenesis." (PMID 36263204, 2022). "Therefore, we speculated that the functions of GSTM2 in colon cancer carcinogenesis might be related to PCDH17 mutation." (PMID 36263204, 2022). "In this study, we demonstrated that PCDH17 expression was elevated in the vascular endothelial cells of colon cancer with distant metastasis." (PMID 39837826, 2025). "Colon cancer tissues with PCDH17-positive ECs rates higher than the median value were defined as the high group, relative to a low group." (PMID 39837826, 2025). "First, PCDH17 was specifically elevated in colon cancer tumor endothelial cells and was positively correlated with clinically distant metastases." (PMID 39837826, 2025). "And, reverse transcription-quantitative polymerase chain reaction (RT-qPCR) analyse indicated that compared with FAM167B, PCDH17 expression was significantly upregulated in vascular endothelial cells isolated from colon cancer than normal tissue (P < 0.05)." (PMID 39837826, 2025). "We found that PCDH17 is the only gene specifically expressed in colon cancer endothelial cells, which is consistent with the public databases." (PMID 39837826, 2025). "We evaluated the correlation between PCDH17 expression in tumor vascular endothelial cells and the clinicopathological characteristics, survival prognosis using a colon cancer tissue microarray by immunofluorescence staining." (PMID 39837826, 2025). "The clinical specimens statistic analysis revealed PCDH17 expression in ECs might be contribute to the metastasis of colon cancer." (PMID 39837826, 2025). "In this study, PCDH17 expression was higher in the vascular endothelial cells of colon cancer with distant metastasis, and the rates of PCDH17+ endothelial cells (ECs) was associated with the M stage in clinical pathological characteristics analysis and correlated with a poor survival prognosis." (PMID 39837826, 2025). "Among the group of the most consistently hypermethylated genes in both human colon cancer and mouse intestinal adenoma (48 genes), we found Cdh4, Crabp1, Crmp1, Dbc1, Duox1, Grm7, Hand1, Hs3st2, Pcdh17 and Pdpn, which have previously been suggested as cancer biomarkers." (PMID 23408899, 2013). "The results using a splenic injection liver metastasis model showed that PCDH17 knockdown significantly decreased the metastasis of tumors to the liver and lungs, indicating that PCDH17 in endothelial cells is closely related to distant metastasis in colon cancer." (PMID 39837826, 2025). "It was shown that protocadherin-17 (PCDH17) silencing via promoter methylation does not only suppresses its role as a tumor-suppressor in inducing apoptosis, but also in inducing JNK-dependent autophagic cell death upon 5-FU treatment in colon cancer." (PMID 34571731, 2021). "Notably, the expression level of PCDH17 in the vascular endothelial cells of colon cancer was significantly elevated compared to that in adjacent normal colon tissues (P < 0.001)." (PMID 39837826, 2025).
esophageal squamous cell carcinoma (4 papers, 2014 to 2020). Esophageal squamous cell carcinoma (ESCC) is a type of esophageal carcinoma (EC) that can affect any part of the esophagus, but is usually located in the upper or middle third. "Reduced PCDH17 expression was observed in esophageal squamous cell carcinoma and was closely linked to hypermethylation in the CpG-rich region." (PMID 33369468, 2020). "In esophageal squamous cell carcinoma (ESCC), PCDH17 was preferentially silenced in poorly differentiated tumors and re-expression of PCDH17 reduced proliferation and migration of ESCC cells." (PMID 30922328, 2019). "Within the same gene cluster as PCDH8 there resides PCDH17 and PCDH20 that are both hypermethylated and homozygously deleted in esophageal squamous cell carcinoma and lung cancer respectively." (PMID 24454902, 2014).
hepatocellular carcinoma (3 papers, 2022 to 2025). A malignant tumor that arises from hepatocytes. "Furthermore, loss of PCDH17 was described to favor metastasis in hepatocellular carcinoma." (PMID 36698136, 2023).
lung carcinoma (3 papers, 2014 to 2024). "We also found that inhibition of PCDH17 promotes cell proliferation, suggesting its tumor-suppressive role in lung cancer." (PMID 33859751, 2021). "We further examined the consequence of demethylation on PCDH17 expression using the demethylating agent 5-aza-dC in four lung cancer cell lines (A549, Calu1, H1299, and HOP62)." (PMID 33859751, 2021). "Moreover, all of the eight novel hypermethylation driver genes (PCDH17, IRX1, ITGA5, HSPB6, TBX5, ADCY8, GALNT13 and TCTEX1D1) were successfully validated in an independent cohort via a pyrosequencing approach, with an AUC of 0.965 for prediction of lung cancer patients." (PMID 33859751, 2021). "Six DMRs located on HOXA9, HOXD3, PCDH17, NID2, NPTX2, and SFRP2 genes exhibiting clinical accuracy over 75% irrespective of lung cancer subtype and cancer progression stages were selected as lung cancer-specific exosome DNA methylation biomarkers." (PMID 39123492, 2024). "The remaining eight genes are newly identified methylation drivers in lung cancer, including 5 known cancer methylation driver genes in other cancer types (HSPB6, IRX1, ITGA5, PCDH17, TBX5) and 3 novel genes that had not been previously reported (ADCY8, GALNT13 and TCTEX1D1)." (PMID 33859751, 2021).